AXL (AXL receptor tyrosine kinase)
Diseases named in the same sentence as AXL in open-access papers (continued):
Sharing a sentence is not in itself a finding about the gene and the disease.
cancer (continued). "This hypothetical model explains broadly documented implication of AXL pathway in drug resistance and cancer metastasis." (PMID 34638349, 2021). "It would be interesting to determine the co-occurrence of Gas6 elevation and PIK3R2 amplification, as well as the corresponding AXL activation status in cancer patients." (PMID 32385243, 2020). "AXL is a receptor tyrosine kinase related to cancer and immune function, which mediates signal transduction related to proliferation and inflammation." (PMID 32580248, 2020). "Several studies have suggested the prognostic and predictive value of two receptor tyrosine kinases (RTKs), MET and AXL, as biomarkers and potential therapeutic targets in cancer treatment." (PMID 34766112, 2020). "Downstream of AXL and TYRO3, numerous intracellular signalling pathways have been associated with cancer progression and drug resistance." (PMID 33059733, 2020). "The binding of HA-MITF was nevertheless enhanced in 4C-HA-MITF cells, with multiple MITFBSs in proximity of several of these cancer-relevant genes (e.g., AXL, IL6, TGFBI, and EGFR,) compared to HA-MITF binding in 3C-HA-MITF." (PMID 32605315, 2020). "Induced expression of AXL is observed in several cancer forms and correlates with disease progression and decreased survival." (PMID 31917795, 2020). "Other microRNAs can regulate AXL in other cancer types, including miR-199a-3p in osteosarcoma and miR-139 in prostate cancer." (PMID 32148495, 2020). "The results suggest that AXL contributes to the stemness of H1299-sdCSCs and is a unique target for cancer prevention with EGCG." (PMID 32051483, 2020). "The role of AXL in cancer progression and angiogenesis is well known, but the role of AXL in VM formation has not been elucidated so far." (PMID 33374832, 2020). "AXL also negatively modulates cancer immune responses through signaling pathways involving dendritic cells, natural killer cells and macrophages." (PMID 33344513, 2020). "During the fractionated and prolonged exposure of radiation, hypoxic cancer cells release master switch HIF-1α to upregulate expressions of pro-angiogenic factors AXL and VEGF." (PMID 32872195, 2020). "The rationale for AXL inhibition in cancer therapy so far has been the frequent overexpression of AXL and the associated poor prognosis in cancers." (PMID 32385243, 2020). "The authors further show that AXL inhibition decreases the activity of these activated macrophages reducing cancer cell invasiveness and restoring drug sensitivity of cancer cells." (PMID 31963783, 2020). "A recent report found that AXL, but not the other two members of the same family MERTK or TYRO3, is cleaved by α- and γ-secretases in cancer cell lines to generate an AXL intracellular isoform." (PMID 32992696, 2020). "AXL (from the Greek “anexelekto” which means “uncontrolled”) is frequently overexpressed in several human cancers (such as breast, lung, gastric, metastatic colon and prostate tumors) and is associated with metastasis and poor prognosis." (PMID 33182542, 2020). "The reduction of sensitivity of hMENA(t) silenced cancer cells to the AXL expression‐dependent BGB324 kinase inhibitor (R428) further confirmed that hMENA silencing induced AXL downregulation." (PMID 32909687, 2020). "Currently, it is still unclear how cabozantinib regulates cancer cell migration and invasion by inhibiting AXL and MET." (PMID 32055714, 2020). "KDM3A transcriptome analysis revealed, in addition to Ets1 and MCAM, other genes previously implicated in the promotion of aggressive cancer properties, including the genes FYN, AXL, LOXL2 and PLAU." (PMID 32577157, 2020). "GAS6/AXL signaling functions as an important pathway driving cancer cell survival, proliferation, migration, and invasion." (PMID 34766112, 2020). "We examined the detection of CK or VIM‐positive AXL‐expressing cancer cells by the MCA system using spike‐in models." (PMID 31999390, 2020).
cancer (continued). "With high CK and low VM‐expressing cell lines, PC‐9 and HCC827, the recovery rate of AXL‐expressing cancer cells was 1%‐17% using either CK or VM as markers." (PMID 31999390, 2020). "miR-34a regulates processes that are essential for tumorigenesis by targeting AXL in malignant tumors." (PMID 33374832, 2020). "MET and AXL were shown to regulate cancer cell growth, migration, invasion, and drug resistance via altering MAPK/ERK, PI3K/AKT, and STAT3 signaling." (PMID 34766112, 2020). "Studies in breast cancer models of lung metastasis have identified that cancer cells with high AXL expression also highly express thrombospondin-2 and this drives TGFβ1-dependent lung colonization." (PMID 33014869, 2020). "AXL has been shown to promote a variety of downstream signaling pathways to mediate its various roles in cancer progression, again, many of which are highly context-dependent." (PMID 32148495, 2020). "Conversely, c-ABL has been shown to mediate apoptosis in response to DNA damage, and sequestration of c-ABL by AXL in the cytoplasm enhances cancer cell survival in EAC cells." (PMID 32922529, 2020). "Growth arrest-specific 6 (GAS6) and hepatocyte growth factor (HGF), the natural ligands of AXL and MET, respectively, are associated with the induction of cancer cell proliferation or metastasis." (PMID 32055714, 2020). "As mentioned, AXL has been previously shown to mediate resistance to various anti-cancer agents, including EGFR, HER2 and PI3K-targeted therapies." (PMID 33059733, 2020). "Recent studies in other cancer contexts suggest that AXL induces NFkB activation in response to a variety of therapies, including kinase inhibitors (22410775, 23474758, and 25568334)." (PMID 32245042, 2020). "Further studies hint at a potential regulatory effect of metformin on the AXL cascade in the context of cancer." (PMID 31822557, 2020). "Precisely, we linked miR-148b to GL21.T, an aptamer able to specifically bind to AXL, an oncogenic tyrosine kinase receptor highly expressed on cancer cells." (PMID 32174798, 2020). "AXL expression strongly correlates with EMT markers across a spectrum of cancer types, including breast, lung, colorectal, bladder, endometrial, and ovarian cancers." (PMID 32148495, 2020). "AXL inhibition in malignant tumors holds the potential to target AXL-mediated epithelial plasticity, stimulate antigen presentation, and block the recruitment of immunosuppressive macrophages to the TIME." (PMID 35582229, 2020). "Given its role in cancer metastasis and immune function, numerous AXL inhibitors are being used in clinical trials to treat advanced malignancies." (PMID 33344513, 2020). "AXL expression and cancer cell invasiveness were confirmed via Boyden chamber assays using serum as a chemoattractant for the four cell lines (data not shown)." (PMID 32055714, 2020). "In many cancer types, overexpression and activation of AXL is generally correlated with malignant progression and poor prognosis." (PMID 33425754, 2020). "AXL is a driver of diverse cellular processes involved in cancer pathogenesis including proliferation, survival, migration, metastasis, dormancy and chemoresistance." (PMID 31694201, 2019). "Given the role of AXL in cancer development, progression and drug resistance, AXL holds great promise as a prognostic biomarker and therapeutic target." (PMID 31684958, 2019). "Overexpression of AXL receptor tyrosine kinase (AXL) in various human cancers correlates with reduced patients overall survival and resistance to first line therapies." (PMID 31171001, 2019). "In this review, we will discuss the basic function of AXL, its major role in controlling the immune system in a normal and cancerous setting, how it contributes to cancer pathogenesis and specifically focus on the role of AXL in hematological malignancies." (PMID 31694201, 2019).
cancer (continued). "Recently, AXL has been reported to play a role in drug resistance mechanisms for many anti-cancer drugs, as well as in ionizing radiation therapy for multiple cancers." (PMID 31043587, 2019). "These experiments demonstrate that pre-treatment of anti-MET antibodies can effectively block the subsequent HGF-mediated AXL co-activation in these cancer cells, and such effects can be detected within less an hour following a 7-minute antibody exposure." (PMID 30760737, 2019). "In radiation-resistant HNSCC cell lines, marked AXL overexpression was found in cancer cell xenografts and patient-derived xenografts (PDXs), whereas resensitization to chemotherapy and radiation was achieved after AXL knockdown." (PMID 31684958, 2019). "Since AXL is considered as an attractive target to overcome the resistance to EGFR-TKIs, several AXL kinase inhibitors, antibody drug conjugates and decoy receptors are currently under investigation in clinical trials for cancer treatment." (PMID 31043587, 2019). "Over the past 5 years, the role of AXL in normal cell biology and cancer cells has been widely investigated." (PMID 31694201, 2019). "Because of the pleiotropic role of AXL in tumour pathophysiology and drug resistance, AXL represents a promising therapeutic target in the management of cancer." (PMID 31684958, 2019). "In hematological malignancies, AXL is generally correlated with a poor prognosis; however, its role in chemoresistance and dormancy is cancer cell specific and remains poorly understood." (PMID 31694201, 2019). "AXL is ubiquitously expressed in various organs and cells and is overexpressed in several human cancers, including lung, colon, esophageal, breast, astrocytoma-glioblastoma, and hematological cancers." (PMID 31497246, 2019). "A significant body of work, therefore, has established AXL as a promising clinical target for managing multiple cancers, and TNBC in particular." (PMID 31007848, 2019). "Altogether, these results suggest that the generated AXL gene signature is representative of AXL depletion in cancer cells and is a valid tool to interrogate pharmacogenomics databases." (PMID 31007848, 2019). "AXL is a receptor tyrosine kinase that plays an important role in the progression of cancer by enhancing proliferation and migration, and inhibiting apoptosis and therapeutic resistance." (PMID 31836741, 2019). "Our lab and others have shown that AXL expression in RAS-driven cancers, such as PDAC, maintains epithelial plasticity." (PMID 31681587, 2019). "GAS6/AXL signalling functions as an important pathway driving cancer cell survival, proliferation, migration and invasion, which makes AXL a potential target in cancer treatment." (PMID 31684958, 2019). "AXL inhibition similarly prevents in vitro and in vivo invasion and migration of many other cancer types including brain, lung, and ovarian cancer." (PMID 30886159, 2019). "For instance, in wild-type EGFR cancer cells, AXL overexpression induces resistance to the anti-EGFR antibody cetuximab via MAPK signaling." (PMID 30651547, 2019). "With respect to the steps of EMT, which are essential for metastasis, the researchers of the present study studied a number of genes reported to have a role in EMT in different cancers, such as Claudin-1, Cofilin-1, AXL, and GAS6." (PMID 31700829, 2019). "Elevated AXL expression is found in multiple cancer types, including lung, breast, ovarian, gastric, colon, pancreatic, and prostate." (PMID 31681587, 2019). "Since AXL plays important roles in cancer progression, it is therefore crucial to elucidate the molecular mechanisms of AXL expression regulation." (PMID 31729427, 2019). "AXL is expressed in many types of cancer and promotes cancer cell survival, metastasis and drug resistance." (PMID 31729427, 2019). "Elevated expression of AXL along with decreased miR-34a expression was observed in several cancer cell lines." (PMID 30386383, 2018).
cancer (continued). "AXL was originally discovered in cancer cells and has been shown to regulate various functions including cell survival and growth, clearance of apoptotic cells, and natural killer cell differentiation." (PMID 30029617, 2018). "We found these cells showed a loss of ALK signaling, overexpressed AXL with epithelial-mesenchymal transition (EMT), and had cancer stem cell-like (CSC) properties, suggesting drug-tolerant cancer cell subpopulations." (PMID 29930762, 2018). "The different ALK-TKI-resistant model used was derived from a different type of cancer and appeared to be similar to that of our study An AXL inhibitor is a promising drug in current development to treat human cancer." (PMID 29930762, 2018). "The increasing knowledge on the role of AXL in regulating several aspects of cancer has justified a growing interest in the development and clinical testing of AXL inhibitors for targeted therapies." (PMID 30353671, 2018). "Our results suggest that therapies targeting key oncogenes BRAF and AXL result in a regain of RIPK3 expression in cancers that have lost it." (PMID 30157175, 2018). "AXL is an important therapeutic target currently being investigated in several cancer clinical trials." (PMID 29719832, 2018). "AXL over-expression has been observed in patients failing PD-1 therapy in several cancers whereas AXL inhibition via bemcentinib has shown synergistic effect with checkpoint blockade in pre-clinical models." (PMID 30400835, 2018). "AXL expression is upregulated during EMT, and the EMT gene program is associated with cells that exhibit normal stem cell and cancer stem cell (CSC) activity." (PMID 29719832, 2018). "Our results reveal a potential role of BRAF and AXL oncogenes in driving the loss of RIPK3 expression and escape from necroptosis in various cancers." (PMID 30157175, 2018). "The dynamic processing of AXL-FL and the subcellular localization of AXL cleavage products not only provide new insights into the diverse functions of AXL, but also open potential new strategies for cancer therapy." (PMID 28034848, 2017). "This is in concordance with prior studies indicating that AXL can drive the growth of cancer cells through the activation of each of these pathways." (PMID 28455956, 2017). "AXL expression was the fourth highest in MPM samples among other cancer types, with a mean log2 value of 11.40." (PMID 29375377, 2017). "Axl expression is also negatively regulated by the microRNAs (miR) miR-34 and miR-199a/b, with an inverse correlation between AXL protein levels and miR-34a expression found in a panel of cancer cell lines." (PMID 28118606, 2017). "Axl receptor tyrosine kinase critically involves in the carcinogenesis of multiple cancers due to its dual roles in both promoting cancer invasion and metastasis and suppressing myeloid cell activation and function." (PMID 29163786, 2017). "The TAM family of proto-oncogenic receptor protein tyrosine kinases, comprising of TYRO3, AXL, and MERTK, is implicated in many human cancers." (PMID 28118606, 2017). "AXL has been reported to be overexpressed or ectopically expressed in a multitude of human cancers, including breast, colon, lung, hepatocellular carcinoma, and esophageal adenocarcinoma." (PMID 28551766, 2017). "AXL-FL is known to be expressed at high levels in several types of cancers, particularly in drug-resistant cancers." (PMID 28034848, 2017). "The cleavage event of AXL in these cancer cells seems to be frequent, as reflected by the substantial amount of AXL-CTF generated from AXL-FL in DAPT-treated samples." (PMID 28034848, 2017). "AXL receptor tyrosine kinase (RTK) inhibition presents a promising therapeutic strategy for aggressive tumor subtypes, as AXL signaling is upregulated in many cancers resistant to first‐line treatments." (PMID 28675785, 2017).
cancer (continued). "Taken together, these data suggest that the proteolytic cleavage of AXL by γ-secretase is widespread across a variety of cancer cells that exhibit high AXL expression levels." (PMID 28034848, 2017). "AXL is upregulated in many cancers being resistant to first‐line treatments, and clinical trials with AXL inhibitors are ongoing in several cancers, including triple‐negative breast cancer (TNBC) and non‐small‐cell lung cancer (NSCLC)." (PMID 28675785, 2017). "Our results indicate that cell softening induced by activation of AXL is an important biophysical property that enhances cancer progression and metastasis." (PMID 29259259, 2017). "Altogether, these findings support the plausibly defeating role of the AXL shedding and intramembrane cleavage for acquired drug resistance in cancer." (PMID 28034848, 2017). "With increasing evidence supporting the role of AXL in resistance to cancer chemotherapy and targeted therapy, many AXL inhibitors, including small molecule inhibitors, anti-AXL monoclonal antibodies, and nucleotide aptamers, are under development." (PMID 28455956, 2017). "And overexpression of AXL is closely associated with expression of EMT-related proteins, such as vimentin, in various cancer models." (PMID 29259259, 2017). "In fact, AXL inhibitors are now under clinical investigation to treat many cancers including metastatic breast cancer." (PMID 28422142, 2017). "Of importance, we have also been able to detect endogenous AXL-ICD in the nuclear fractions of H1299 or Panc-28 cancer cells, whereas AXL-FL was undetected in the nucleus." (PMID 28034848, 2017). "These genes included ANKLD1, AXL, CAV1/2, LDHB, ETS1, IFI16, PTRF (cavin), KIAA1199 and VIM, which have previously been linked to drug resistance in breast and other cancers." (PMID 26646320, 2016). "As a result, there are a variety of AXL inhibitors that are in preclinical and clinical development for the treatment of cancer." (PMID 27834845, 2016). "The importance of YAP/TAZ target genes such as CTGF, CYR61, AXL and others for cancer progression was already demonstrated." (PMID 26876920, 2016). "In this review we will highlight recent literature describing the role of GAS6/AXL signaling in cancer progression." (PMID 27834845, 2016). "Our previous data and other studies have identified a role for AXL in cancer cell migration/invasion and showed that AXL levels are required for niche activation and the first phase of metastatic colonization." (PMID 27793046, 2016). "MEK inhibition was shown to decrease AXL shedding on cancer cells by inhibiting ADAM10 catalytic activity through the activation of TIMP1, a negative regulator of ADAM10." (PMID 27834845, 2016). "In fact, AXL-specific inhibitors and multi-kinase inhibitors targeting AXL are already under development for treatment of several cancers." (PMID 27764792, 2016). "Most importantly, this work has led to the development of a variety of GAS6/AXL inhibitors that have been tested in preclinical and clinical studies and are promising new therapeutic strategies for cancer therapy." (PMID 27834845, 2016). "AXL aberration is reportedly a marker for poor prognosis and treatment resistance in various cancers." (PMID 27100677, 2016). "To evaluate the potential role of AXL in the regulation of cancer-related inflammation in TNBC, we analyzed co-regulated genes and pathways using the SEEK platform and the Ingenuity Pathway Analysis software." (PMID 28721387, 2016). "More specifically, the biological role of AXL, a receptor tyrosine kinase, in EC remains largely uncharacterized despite its promising advances in numerous cancers." (PMID 27764792, 2016). "Several classes of AXL inhibitors have been developed and have shown efficacy in preclinical models of cancer." (PMID 27834845, 2016). "In cutaneous squamous cell carcinoma cell lines, AXL expression correlates with the cancer stem cell markers CD44 and ALDH1, increased resistance to chemotherapy, and enhanced sphere formation." (PMID 27834845, 2016).